Y_RNA (Y RNA )
Gene: Miscellaneous RNA gene on chromosome 9 (37,322,259 to 37,322,371, forward strand). Ensembl gene ENSG00000206784.
Homologues: Orthologues: chimpanzee Y_RNA (96% identical), macaque Y_RNA (96% identical). Paralogues in human: RNY1 (87% identical), Y_RNA (84% identical), Y_RNA (83% identical), RNY1P11 (82% identical), Y_RNA (82% identical), RNY1P10 (81% identical), Y_RNA (81% identical), RNY1P7 (81% identical), RNY1P8 (80% identical), Y_RNA (80% identical), Y_RNA (79% identical), RNY1P13 (78% identical), and 94 more.